FGF17 (fibroblast growth factor 17)
Description:
Plays an important role in the regulation of embryonic development and as signaling molecule in the induction and patterning of the embryonic brain. Required for normal brain development.
Synonyms: FGF-17; FGF-13; HH20
Tractability: Antibody: its Gene Ontology location is reachable by antibodies, with high confidence; UniProt places it where antibodies can reach, with medium confidence; UniProt predicts a signal peptide or a membrane-spanning region.
Gene: Protein-coding gene on chromosome 8 (22,042,398 to 22,048,809, forward strand). Ensembl gene ENSG00000158815.
Subcellular location: Secreted
Pathways (Reactome):
Signal Transduction: Downstream signaling of activated FGFR1; FGFR1c ligand binding and activation; FGFR2c ligand binding and activation; FGFR3b ligand binding and activation; FGFR3c ligand binding and activation; FGFR4 ligand binding and activation; FGFRL1 modulation of FGFR1 signaling; FRS-mediated FGFR1 signaling; FRS-mediated FGFR2 signaling; FRS-mediated FGFR3 signaling; FRS-mediated FGFR4 signaling; Negative regulation of FGFR1 signaling; Negative regulation of FGFR2 signaling; Negative regulation of FGFR3 signaling; Negative regulation of FGFR4 signaling; PI-3K cascade:FGFR1; PI-3K cascade:FGFR2; PI-3K cascade:FGFR3; PI-3K cascade:FGFR4; PI3K Cascade; PI5P, PP2A and IER3 Regulate PI3K/AKT Signaling; PIP3 activates AKT signaling; Phospholipase C-mediated cascade: FGFR1; Phospholipase C-mediated cascade; FGFR2; Phospholipase C-mediated cascade; FGFR3; Phospholipase C-mediated cascade; FGFR4; RAF/MAP kinase cascade; SHC-mediated cascade:FGFR1; SHC-mediated cascade:FGFR2; SHC-mediated cascade:FGFR3; SHC-mediated cascade:FGFR4
Disease: Activated point mutants of FGFR2; Constitutive Signaling by Aberrant PI3K in Cancer; Signaling by FGFR1 in disease; Signaling by FGFR2 in disease; Signaling by FGFR3 in disease; Signaling by activated point mutants of FGFR1; Signaling by activated point mutants of FGFR3
Gene Ontology:
Molecular function: protein binding; type 1 fibroblast growth factor receptor binding; type 2 fibroblast growth factor receptor binding; growth factor activity
Biological process: cell-cell signaling; fibroblast growth factor receptor signaling pathway; nervous system development; neurogenesis; positive regulation of cell population proliferation; positive regulation of MAPK cascade; regulation of cell migration; signal transduction
Cellular component: cytoplasm; extracellular region
Genetic constraint (gnomAD): Loss-of-function variants: 5 observed, 23.39 expected, observed/expected ratio (o/e) 0.21, 90% interval 0.11 to 0.45. The upper end of that interval is the gene's LOEUF score, 0.45, which puts it in group 1 of 6, group 1 being the genes least tolerant of losing a copy. Missense variants: 216 observed, 316.47 expected, observed/expected ratio (o/e) 0.68, 90% interval 0.61 to 0.76. Synonymous variants: 132 observed, 125.59 expected, observed/expected ratio (o/e) 1.05, 90% interval 0.91 to 1.21.
Homologues: Orthologues: chimpanzee FGF17 (100% identical), dog FGF17 (99% identical), mouse Fgf17 (99% identical), rat Fgf17 (99% identical), guinea pig FGF17 (98% identical), pig FGF17 (98% identical), rabbit FGF17 (50% identical). Paralogues in human: FGF8 (58% identical), FGF18 (47% identical), FGF20 (23% identical), FGF6 (22% identical), FGF10 (22% identical), FGF22 (22% identical), FGF3 (21% identical), FGF9 (21% identical), FGF13 (20% identical), FGF4 (20% identical), FGF7 (20% identical), FGF16 (19% identical), and 9 more.
Diseases named in the same sentence as FGF17 in open-access papers:
FGF17 is named in the same sentence as 27 diseases in open-access papers, as found by Europe PMC text mining. Sharing a sentence is not in itself a finding about the gene and the disease. The quoted sentences say what the papers report.
hepatocellular carcinoma (3 papers, 2016 to 2025). A malignant tumor that arises from hepatocytes. "FGFR4, the key functional receptor of FGF17, is overexpressed in several cancers, including NSCLC, colorectal, breast, and hepatocellular carcinoma, and is closely linked to unfavorable patient outcomes." (PMID 41551579, 2025). "In hepatocellular carcinoma, FGF8 subfamily members, including FGF8, FGF17 and FGF18, were upregulated to facilitate cell survival and angiogenesis via activating ERK." (PMID 30082912, 2019). "FGF8 and FGF10 are involved in embryonic liver development, FGF7 and FGF9 in repair in response to liver injury, and FGF5, FGF8, FGF9, FGF17, and FGF18 in the development and progression of hepatocellular carcinoma." (PMID 27148532, 2016). "In addition, FGF5, FGF8, FGF9, FGF17, and FGF18 play roles as paracrine signals in the development and progression of hepatocellular carcinoma." (PMID 27148532, 2016).
Anosmia (2 papers, 2014 to 2020). An inability to perceive odors. "PCSK1 and POLR3B are associated with normosmic CHH, but FGF17 mutations are associated with KS and anosmia, which implies a role during early GnRH neuron migration from the olfactory placodes as well." (PMID 31996360, 2020).
prostate carcinoma (2 papers, 2008 to 2011). A carcinoma that arises from epithelial cells of the prostate gland. "FGF17 is upregulated in some prostate cancers and this correlates with a higher risk of metastases and lower survival." (PMID 18840272, 2008). "In prostate cancer, FGFR1 and FGFR4 as well as the ligands FGF-1, FGF-2, FGF-6, FGF-8, FGF-9, and FGF-17 are all known to be over-expressed." (PMID 22078327, 2011).
schizophrenia (2 papers, 2021 to 2023). A major psychotic disorder characterized by abnormalities in the perception or expression of reality. "They identified GPC1 as a candidate risk factor for schizophrenia and proposed a model, in which epistatic interactions between GPC1 and FGF17 during brain development are involved in the etiology of schizophrenia." (PMID 33679334, 2021). "Among the 7 DEGs, the TNC gene was the only gene that decreased with schizophrenia and showed a positive correlation with PI (16:0/20:4), while the other 6 DEGs (COL1A2, COL6A2, DDIT4, FGF17, GNB3, and PDGFRB) increased with schizophrenia and showed a negative correlation with PI (16:0 /20:4)." (PMID 37143779, 2023).
acute myeloid leukemia (1 paper, 2023). Acute myeloid leukemia (AML) is a group of neoplasms arising from precursor cells committed to the myeloid cell-line differentiation. "Furthermore, FGF10/FGF17 has been identified as a prognostic and drug response marker in acute myeloid leukemia, suggesting that small-molecule inhibitors of FGF10 and FGF17 are promising therapeutic targets." (PMID 37108717, 2023).
anal carcinoma (1 paper, 2014). "FGF17 either enhances cellular proliferation or inhibits apoptosis and EGFR induces signaling pathway in different kinds of cancer, namely, lung and anal cancer." (PMID 24967385, 2014).
autism (1 paper, 2018). Persistent deficits in social interaction and communication and interaction as well as a markedly restricted repertoire of activity and interest as well as repetitive patterns of behavior. "Reduced preference for social novelty has also been seen in mouse models associated with autism, including KOs of NLGN4 and FGF17 genes." (PMID 29920554, 2018).
breast carcinoma (1 paper, 2018). "IL-6, VEGF, and TGF-β1 have been proved to be commonly overexpressed in human breast cancer cases, FGF10 played the important role in type III epithelial-mesenchymal transition (EMT) on breast cancer cells and initiation of metastasis, and high expression of FGF17 causes tamoxifen resistance." (PMID 29581982, 2018).
breast tumour (1 paper, 2008). "Since NPM2 and FGF17 were over-expressed in two cancer cell lines, expression levels were analysed in 61 primary tumours, from the primary breast tumour series analysed by FISH, for which cDNA was available." (PMID 18840272, 2008).
cervical cancer (1 paper, 2023). A primary or metastatic malignant neoplasm involving the cervix. "In turn, SCs activation leads to PNI of cervical cancer by secreting FGF17, CTSS and MMP‐12." (PMID 37830980, 2023). "Therefore, FGF17 might play a critical role in PNI of cervical cancer." (PMID 37830980, 2023). "Moreover, SCs displayed increased protein expression of FGF17, CTSS and MMP‐12 after co‐cultivation with cervical cancer cells." (PMID 37830980, 2023).
hypogonadism (1 paper, 2021). A disorder characterized by decreased function of the gonads. "FGF17 gene plays a role in the differentiation of granulosa cells and also in hypogonadism." (PMID 34887899, 2021).
hypogonadotropic hypogonadism (1 paper, 2023). Abnormal ovarian or testicular function due to insufficient hormonal stimulation from the hypothalamic-pituitary axis. "Although we identified rare or novel missense variants in several hypogonadotropic hypogonadism genes (e.g. FGF17, HS6ST1, KISS1R, CHD7, IL17RD) definitively linking them to the PSIS phenotype is premature." (PMID 38096238, 2023).
hypospadias (1 paper, 2022). Hypospadias is the displacement of the urethral meatus on the ventrum of the penis. "And FGF17 has high homology to FGF8, while FGF8 signaling is required for genital tubercle (GT) proximal-distal outgrowth, as abolishing FGF8 or its receptors leads to GT agenesis in mice, resulting in hypospadias." (PMID 35669683, 2022).
kidney cancer (1 paper, 2021). Primary or metastatic malignant neoplasm involving the kidney. "In addition, we performed qRT-PCR analysis on clinical specimens and found that the mRNA expression levels of FGF17, PRKCG, and SSTR1 were significantly different between kidney cancer tissues and normal tissues adjacent to the cancer." (PMID 35155566, 2021).
lymph node metastasis (1 paper, 2025). "Consistent clinical data further demonstrated that FGF17 upregulation was associated with higher TNM stages and the presence of lymph node metastasis." (PMID 41551579, 2025).
omphalocele (1 paper, 2020). Omphalocele is an embryopathy classified in the group of abdominal celosomias and is characterized by a large hernia of the abdominal wall, centered on the umbilical cord, in which the protruding viscera are protected by a sac. "The results we have obtained thus far present something of a conundrum: how does the loss of Fgf8 and Fgf17 in the PSM cause omphalocele at E13.5 and later?" (PMID 32907848, 2020). "Consistent with the hypothesis that omphalocele is multifactorial in origin, we find that Fgf8 and Fgf17 are needed in the PSM whereas Fgf18 is required in the somites." (PMID 32907848, 2020). "From these results we conclude that the requirement for Fgf8 expression is in the PSM; the hypothesis that Fgf8 is required in the PSM is further supported by the fact that loss of Fgf17 in TCre;Fgf8f/Δ mutants promoted omphalocele, and Fgf17 is expressed in the PSM but not the somites." (PMID 32907848, 2020).
ovarian carcinoma (1 paper, 2025). A malignant neoplasm originating from the surface ovarian epithelium. "The findings indicated that the expression of FGF17 was notably higher in ovarian cancer tissue when compared to normal lung tissue." (PMID 41551579, 2025).
polyp (1 paper, 2024). A usually exophytic mass attached to the underlying tissue by a broad base or a thin stalk. "Significant dysregulation of the expression of critical genes, including DKK1, GPC3, BMP7, FGF17, and WNT10B, was observed in the PPI network; this dysregulation could potentially be associated with the proliferation of polyp tissues." (PMID 38473810, 2024).
renal carcinoma (1 paper, 2021). A carcinoma arising from the epithelium of the renal parenchyma or the renal pelvis. "Interestingly, the gene probes targeting FGF17, PRKCG, SSTR1, and SCTR predicted potential targeted agents for renal cancer metastasis and adjuvant immunotherapy, including 5224221, calmidazolium, and sulfasalazine." (PMID 35155566, 2021).
rheumatoid arthritis (1 paper, 2024). A chronic, systemic autoimmune disorder characterized by inflammation in the synovial membranes and articular surfaces. "Interestingly, B. burgdorferi uniquely bound a protein associated with rheumatoid arthritis (PGLRP1 16), and B. bavariensis uniquely bound several proteins found in the central nervous system (FGF17 and multiple neuropeptides)." (PMID 38876107, 2024).
cancer (10 papers, 2008 to 2025). A tumor composed of atypical neoplastic, often pleomorphic cells that invade other tissues. "This indicates that FGF17 facilitates the migration and invasion of cancer cells through sustaining glutamine metabolism and supporting α-KG-driven TCA cycle activity, further confirming its intervention in metabolic reprogramming during NSCLC progression." (PMID 41551579, 2025). "FGF17 and PDGF are two major growth factors that regulate the PI3K/Akt pathway and are associated with its activation during cancer progression." (PMID 40766751, 2025). "In addition, we observed a weak induction of FGF17 in all three cancer cell lines, though only at low levels, which could be detected by RT-PCR after extended rounds of amplification, but not by ELISA of either supernatant or cell lysate." (PMID 30237393, 2018). "FGF17, as a member of the fibroblast growth factor (FGF) family, was located at 8p21.3 and played a significant role in the occurrence and progression of cancer (Tabarés-Seisdedos and Rubenstein, 2009)." (PMID 35155566, 2021). "In summary, we found significant differences in the expression of FGF17, PRKCG, SSTR1, and SCTR in cancer, which are correlated with immune response and adjuvant therapy." (PMID 35155566, 2021). "The upregulation of fibroblast growth factor 17 (FGF17) and epidermal growth factor receptor (EGFR) by genistein clearly indicated the stimulation of different signaling pathways which have been known to be involved in cancer." (PMID 24967385, 2014). "Functional and mechanistic analyses revealed that silencing FGF17 suppressed the FGFR4/MEK5/ERK5 signaling cascade, disturbed NRF2-dependent redox homeostasis, and consequently impaired epithelial–mesenchymal transition (EMT), leading to a marked reduction in cancer cell motility and invasiveness." (PMID 41551579, 2025).
tumor (10 papers, 2008 to 2025). "Additionally, FGF17 levels were significantly associated with the serum tumor markers CA125 and CEA (with a correlation coefficient r ranging from 0.5 to 0.7 and p < 0.001)." (PMID 41551579, 2025). "The analysis of the protein expression patterns of FGF17 in both normal and tumor tissues was carried out by utilizing the human protein atlas (HPA) database." (PMID 41551579, 2025). "A significant relationship was identified between FGF17 expression levels and the percentage of PD-L1-positive cells in tumor tissues, as verified by the clinical cohort study." (PMID 41551579, 2025). "Molecular validation revealed a marked reduction of FGF17 protein levels in tumor samples from the shFGF17 group (p < 0.001), accompanied by concurrent suppression of its receptor FGFR4 and downstream p-MEK5 and p-ERK5 (Thr218/Tyr220) (p < 0.05)." (PMID 41551579, 2025). "FGF17 is involved in broad biological processes, including embryonic development, tissue repair, cell growth, tumor growth, and invasion." (PMID 39766329, 2024). "This study aims to explore how FGF17 expression affects migration of NSCLC tumor cells." (PMID 41551579, 2025). "This omission might have hindered a comprehensive portrayal of GLUL and FGF17 expression within the tumor microenvironment." (PMID 41551579, 2025). "Both studies have reported that FGF17 may be a novel tumor-promoting gene whose expression is upregulated in neoplasms, data which contradicted our findings." (PMID 34335699, 2021). "Collectively, our findings demonstrated that in tumor cell glutamine metabolism, the GLUL-mediated FGF17/FGFR4/MEK5/ERK5 signaling axis sustains redox homeostasis in the tumor microenvironment via activation of NRF2-dependent antioxidant programs." (PMID 41551579, 2025). "Cellular functional and mechanistic studies indicated that FGF17 knockdown inhibited the FGFR4/MEK5/ERK5/NRF2 signaling axis, disrupted redox balance, and suppressed EMT progression, thereby reducing tumor cell migration and invasion." (PMID 41551579, 2025). "The dedifferentiated Schwann cell overexpressed FGF17, which subsequently led to the production of Cathepsin S and MMP-12-mediated extracellular matrix degradation, inducing tumor metastasis." (PMID 39766329, 2024). "PPI network analysis revealed these genes and modules were mainly related to tumor progression (LOXL1, IKBKE, LNX1, FOXA2, FGF17, and FGF2) and immune response (STAT4, IL23R, LTA, ITK, and IL19)." (PMID 36611170, 2023). "FGF17, PRKCG, and SSTR1 were detected with the same results in tumor tissues and adjacent normal kidney tissues, while SCTR was not significantly different." (PMID 35155566, 2021). "Furthermore, overexpression of FGF12, FGF14, FGF17, FGFR1, FGFBP3 and IGFBPL1 genes was found in early tumor stage, while, overexpression of IGF1R, IGF2BP2 and INSRR was found in advanced tumor stages." (PMID 34061869, 2021). "Subsequently, through OCLR scores, it was further confirmed that the expressions of FGF17, PRKCG, SSTR1, and SCTR were different in KIRC, which might lead to tumor metastasis by promoting tumor dedifferentiation." (PMID 35155566, 2021). "Interestingly, ligands for this receptor, FGF2, FGF17, FGF8, and FGF19, were also overexpressed in the tumour." (PMID 26998479, 2015). "Finally, although FGF17’s role in NSCLC was confirmed using both in vitro and in vivo systems, it remains unclear whether these models accurately reflect the human NSCLC tumor microenvironment." (PMID 41551579, 2025). "Collectively, these results confirmed that glutamine metabolism in NSCLC activates the FGF17/MEK5/ERK5/NRF2 signaling pathway via GLUL, thereby lowering oxidative stress levels in the tumor microenvironment and enhancing migratory and invasive capacities of tumor cells." (PMID 41551579, 2025). "None of the tumours expressed FGF17 above the range of the control groups." (PMID 18840272, 2008).
tumor (continued). "FGF17, natriuretic peptide A (NPPA), SHC2, and WAP, follistatin/kazal, immunoglobulin, kunitz, and netrin domain containing 1 (WFIKKN1) was not expressed or at a minimal level in tumor tissues." (PMID 34335699, 2021).
FGF17 also shares sentences with these, for which no sentence is quoted: cleft lip (1 paper); colorectal cancer (1); non-small cell lung carcinoma (1); Noonan syndrome (1); Parkinson disease (1).